OR4K14 (olfactory receptor family 4 subfamily K member 14)
Description:
Odorant receptor.
Synonyms: OR14-18; OR14-22
Tractability: Antibody: UniProt places it where antibodies can reach, with medium confidence; UniProt predicts a signal peptide or a membrane-spanning region; its Gene Ontology location is reachable by antibodies, with medium confidence.
Gene: Protein-coding gene on chromosome 14 (20,014,143 to 20,019,307, reverse strand). Ensembl gene ENSG00000169484.
Subcellular location: Cell membrane
Pathways (Reactome):
Sensory Perception: Expression and translocation of olfactory receptors
Gene Ontology:
Molecular function: olfactory receptor activity; G protein-coupled receptor activity
Biological process: detection of chemical stimulus involved in sensory perception of smell; G protein-coupled receptor signaling pathway
Cellular component: plasma membrane; membrane
Genetic constraint (gnomAD): Missense variants: 384 observed, 369.7 expected, observed/expected ratio (o/e) 1.04, 90% interval 0.95 to 1.13. Synonymous variants: 147 observed, 143.46 expected, observed/expected ratio (o/e) 1.02, 90% interval 0.89 to 1.17.
Homologues: Orthologues: dog OR4K14 (85% identical), rabbit OR4K14 (84% identical). Paralogues in human: OR4K15 (67% identical), OR4K13 (66% identical), OR4K1 (62% identical), OR4K2 (61% identical), OR4K5 (61% identical), OR4K17 (60% identical), OR4L1 (58% identical), OR4F5 (56% identical), OR4F4 (56% identical), OR4F17 (56% identical), OR4Q3 (54% identical), OR4F6 (53% identical), and 116 more.
Diseases named in the same sentence as OR4K14 in open-access papers:
OR4K14 is named in the same sentence as 1 disease in open-access papers, as found by Europe PMC text mining. Sharing a sentence is not in itself a finding about the gene and the disease.
OR4K14 shares sentences with these, for which no sentence is quoted: bipolar disorder (1 paper).